CCL2 (C-C motif chemokine ligand 2)
Diseases named in the same sentence as CCL2 in open-access papers (continued):
Sharing a sentence is not in itself a finding about the gene and the disease.
neuropathy (26 papers, 2010 to 2025). A disorder affecting the nervous system that manifests with pain, tingling, numbness, and/or muscle weakness. "Currently, it is known that CCL2 can also be secreted by cells involved in neuropathy development, such as microglia, macrophages, and neutrophils." (PMID 37570736, 2023). "They both activate glial and immune cells to release proinflammatory cytokines such as TNF-α, IL-1β, IFN-γ, and IL-6, and chemokines such CCL2 and CCL5, which cause neuronal hyperexcitability, neurodegeneration, neuropathies including neuropathic pain." (PMID 35095888, 2021). "CCL2 increases the sensitivity of neurons in other models of neuropathic pain, and probably the same mechanism can be observed in neuropathy induced by chemotherapeutics." (PMID 30909387, 2019). "The CCR2/CCL2 system has been identified as a regulator in the pathogenesis of neuropathy-induced pain." (PMID 21143971, 2010). "High systemic levels of CCL2 might thus correlate with the development of neuropathic symptoms and could serve as a severity marker of the neuropathy." (PMID 36860843, 2023). "Additionally, the inhibition of CCL2 in the spinal cord reduced mechanical hypersensitivity in a post-stroke animal model of neuropathy." (PMID 37570736, 2023). "Severe neuropathy indicated by a low SNAP correlated with high gene expression of CCL2." (PMID 36860843, 2023). "In addition, we observed higher plasma concentrations of CCL2 in patients with grade 3 neuropathy (mean ± SD; 230.31 ± 97.80) compared with patients with grade 1 neuropathy (mean ± SD; 219.62 ± 109.44), though statistically insignificant." (PMID 34640602, 2021). "Furthermore, while CCL2 expression is upregulated in a number of neuropathies, the consequences are detrimental in some disease states and protective in others." (PMID 25012628, 2014). "CCL2 is known to activate microglia in other neuropathies, leading to a proinflammatory response." (PMID 25012628, 2014). "In addition, CCL2 could induce the activation of microglia in various neuropathies and lead to a proinflammatory response." (PMID 28870240, 2017). "We observed greater induction of SCN CCL2, along with greater SCN CD11b levels in males than females during neuropathy." (PMID 31763376, 2019). "In our study, we have shown that the levels of two highly pronociceptive chemokines that change in neuropathy, CCL2 and CCL5, did not increase in animals repeatedly receiving mirogabalin." (PMID 37513935, 2023). "In the group without neuropathy during treatment, a moderate positive correlation was found between the concentration of CCL2 in the plasma and WBC (rs = 0.561)." (PMID 34640602, 2021). "In the group with neuropathy during treatment, we observed interesting moderate-positive correlations between kappa FLCs and the expression of the IFN-γ gene (rs = 0.447) and between lambda FLCs and the concentration of CCL2 in the plasma (rs = 0.414)." (PMID 34640602, 2021). "Moreover, taking into consideration our results and aforesaid literature, all three chemokines acting via CCR4, that is, CCL17, CCL22, and CCL2, seem to be important mediators in pathological nociceptive processes at the DRG level under neuropathy." (PMID 32760393, 2020). "In contrast, the molecular link between the chemokine CCL2 and hyperalgesia in the absence of neuropathy is more controversial." (PMID 23658840, 2013). "Furthermore, the serum cytokine profiles of CTS patients were readily distinguishable from those of controls with distinct patterns of the chemokines CCL2, CCL4, CCL5, CXCL8 and CXCL10 and the growth factors VEGF, PDGF and G-CSF, which may be induced by the neuropathy." (PMID 28811623, 2017). "Our analysis identified increased concentrations of CCL2, IL-1β, and IFN-γ in plasma of MM patients during treatment, both with and without symptoms of PN, compared with untreated neuropathy-free MM patients." (PMID 34640602, 2021).
SARS-CoV infection (26 papers, 2008 to 2023). "CCL2 protein expression has been associated with early inflammatory host responses during murine SARS-CoV infection." (PMID 23029269, 2012). "An earlier study after the SARS-Cov epidemic showed that the G-2518A codon variants CCL2 (rs1024611) and MBL54 (rs1800450) had a significant cumulative effect on increased susceptibility to SARS-CoV infection." (PMID 35327350, 2022). "A functional single nucleotide polymorphism in CCL2 which results in higher expression of the chemokine has also been reported to be an independent risk factor for increased susceptibility to SARS-CoV infection, but not mortality." (PMID 33613280, 2020). "Interestingly, the temporal expression patterns of 4 IRGs (ISG15, IFI44, PSME2 and CCL2) were similar amongst the SARS-CoV infection-reinfection experiments (50 IRGs) and this list of 8 IRGs from the adjuvanted vaccine–challenge experiments." (PMID 23029269, 2012). "Moreover, four IRGs (ISG15, IFI44, PSME2 and CCL2) were expressed in common between the SARS-CoV infection-reinfection experiments and these 8 IRGs." (PMID 23029269, 2012). "In a MERS-CoV infection, the epithelial and endothelial cells induced significant but delayed IFN and pro-inflammatory cytokine (IL-1β, IL-6 and IL-8) responses, while a large quantity of CCL3, CCL5, CCL2, and CXCL10 was produced during a SARS-CoV infection." (PMID 36016187, 2022). "As compared to the SARS-CoV infection, MERS-CoV infection induced significantly higher expression levels of IL-8, IL-12, IP-10/CXCL-10 and MCP-1/CCL-2." (PMID 34876129, 2021). "In additional cell-based studies, SARS-CoV infection induced expression of CXCL8 and CCL2 in A549 lung epithelial cells and THP-1 monocytic cells." (PMID 33613280, 2020). "SARS-CoV infection of myeloid dendritic cells, even unproductive, leads to chemokines upregulation of CXCL10 (IP-10), CCL2 (MCP-1), CCL3 (MIP-1a) and CCL5 (RANTES)." (PMID 32962761, 2020). "Despite an abortive infection, the SARS-CoV infection in human macrophages induced the expression of a number of proinflammatory chemokines including IP-10/CXCL10 and MCP-1/CCL2." (PMID 26690369, 2015). "EBN also attenuated the surge in pro-inflammatory cytokines and chemokines such as TNF-α, CCL-2, NF-κβ, NO, IL-6, and increased IFN-γ, which are dysregulated in severe forms of IAV, and SARS-CoV infections." (PMID 34025406, 2021). "Another downregulated gene in the SARS-CoV infection is nitric oxide synthase traffic inducer (NOSTRIN) so this downregulation can induce the secretion of some proinflammatory chemokines and cytokines including CCL2, CCL5, and IL-6." (PMID 32754004, 2020). "Lung autopsies of SARS patients and in vitro SARS-CoV infections of macrophages and alveolar and bronchial cells have clearly demonstrated upregulation of numerous monocyte/macrophage, neutrophil and T cell-specific chemokines, including CCL2, CCL5, CXCL8, CXCL9 and CXCL10." (PMID 33613280, 2020). "Immune cell—recruiting chemokines and cytokines, such as IP-10/CXCL-10, MCP-1/CCL-2, MIP-1α/CCL-3, RANTES/CCL-5, can be strongly induced by MERS-CoV, showing higher inducibility in human monocyte—derived macrophages by MERS-CoV as compared to than SARS-CoV infection." (PMID 32522207, 2020). "Two IFN-induced chemokines, CCL2 and CXCL10, were significantly upregulated in the lung at 5–7 DPI with SARS-CoV infection but not after reinfection." (PMID 23029269, 2012).
cardiac hypertrophy (25 papers, 2011 to 2025). "Astragaloside IV (AS-IV) alleviates HF by inhibiting CCL2-mediated NF-κB signaling pathway activation, reducing LPS-induced myocardial hypertrophy and collagen deposition." (PMID 39165261, 2024). "Collectively, these results indicate that TFRC in cardiomyocytes recruits and activates macrophages by secreting Ccl2 in the process of pathological cardiac hypertrophy." (PMID 37647427, 2023). "TFRC in cardiomyocytes recruits and activates macrophages by secreting CCL2 to induce myocardial hypertrophy and promote HF development." (PMID 38034382, 2023). "Elevated levels of CCL2 are found in cardiac biopsies from patients with cardiac hypertrophy due to aortic stenosis." (PMID 27525724, 2016). "Furthermore, TFRC in cardiomyocytes recruits and activates macrophages by secreting C‐C motif ligand 2 (Ccl2) in the mice heart tissue with TAC surgery or in the primary cardiomyocytes stimulated with ISO or PHE to induce myocardial hypertrophy in vitro." (PMID 37647427, 2023). "Ccl2 mRNA and protein expression levels were significantly increased in the primary cardiomyocytes treated with ISO or PHE to induce myocardial hypertrophy in vitro." (PMID 37647427, 2023). "Next, we measured genes typically upregulated in pathological cardiac hypertrophy: genes regulating collagen synthesis (Col1a1, Col3a1, Col8a1, and Ccl2) were not altered by diet." (PMID 35736495, 2022). "In fact, many factors such as CCL-2, CCL-3, and CCL-5, whose gene expression was highly increased in preconditioned MSCs, were reported to be upregulated in patients with structural remodeling including hypertrophy and congestive heart disease." (PMID 33927770, 2021). "Levels of circulating CCL2, CCL3, and CCL5 chemokines are high in patients with cardiac hypertrophy and congestive heart failure, and CCL21 is found at significantly higher than normal levels in the serum of patients with LVH due to aortic stenosis and pressure overload." (PMID 27525724, 2016).
cyst (25 papers, 2014 to 2026). A sac-like closed membranous structure that may be empty or contain fluid or amorphous material. "CCL2-overexpressing Arabidopsis plants showed significantly reduced susceptibility to the cyst nematode H. schachtii." (PMID 33897746, 2021). "Early studies have documented kidney interstitial inflammation and fibrosis in ADPKD, with pro-inflammatory molecules, namely TNF-α and MCP-1/CCL2, being present in high concentrations in the urine and cyst fluids." (PMID 39940890, 2025). "In ADPKD, after knockdown of Pkd1 or Pkd2, C-C motif chemokine ligand 2 (CCL2) was highly upregulated at the onset of cyst formation." (PMID 37583898, 2023). "Our results demonstrate that expression of CCL2 enhances host resistance against the cyst nematode Heterodera schachtii." (PMID 33897746, 2021). "Overexpression of CCL2 in Arabidopsis improved plant growth and general disease resistance toward the cyst nematode H. schachtii and various plant pathogens." (PMID 33897746, 2021). "Knocking out CCL2 in the renal tubular cells decreases macrophage infiltration into the kidney and ameliorates cyst formation in ADPKD34." (PMID 32528023, 2020). "P21 mutants had more widespread Ccl2 expression, mostly in minimally dilated tubules, but occasionally in cyst lining cells." (PMID 27853247, 2016). "Interestingly, LKB1 (STK11) was shown to be part of a ciliary module comprising NPHP1, NEK7, ANKS3 and polycystin-1 that regulates cilia-controlled secretion of CCL2, a chemokine that promotes macrophage recruitment and consequent cyst growth and interstitial inflammation." (PMID 34055783, 2021). "More interestingly, we found that cyst fluid and high iron consistently upregulated the expression of IL8 and VEGFA and downregulated the expression of TNFα and CCL2 inTHP-1 cells." (PMID 36547083, 2022). "At P21, Ccl2 protein was ectopically expressed most robustly in minimally-dilated mutant proximal tubules, and to a lesser degree in LTL-positive cyst-lining cells." (PMID 27853247, 2016). "MCP-1/CCL2 also influences adaptative immunity, both by inducing TH2 differentiation and IL-4 secretion, resulting in the M1 to M2-like phenotype macrophage switch that further drives tubular proliferation and cyst growth in ADPKD." (PMID 39940890, 2025). "Although a large fraction of FR-PTC did not originate from cyst-lining cells but rather injured tubules, they still expressed proinflammatory (CCL2) or profibrotic (TGFB2) molecules, suggesting that they may be contributing to interstitial inflammation and fibrosis even though they are not cystic." (PMID 36310237, 2022). "In this study, we had not systematically investigated the effects of iron on macrophage polarization, but we found there were higher expressions of IL8 and VEGF, lower expressions of TNFα and CCL2, and no change in IL1b and IL6 in the macrophages treated with cyst fluid and iron." (PMID 36547083, 2022). "Thus, the ectopic Ccl2 signal in Six2creFrs2αKO kidneys emanates from non-dilated proximal tubules at P7 and from both LTL-positive non-dilated and cyst lining cells later." (PMID 27853247, 2016).
Glucose intolerance (25 papers, 2011 to 2026). Glucose intolerance (GI) can be defined as dysglycemia that comprises both prediabetes and diabetes. "In this study, miR-452 with common target sequence in RETN, TNFα, and CCL2 mRNAs could contribute to worsening glucose intolerance in the IH-condition by up-regulation of RETN, TNFα, and CCL2 mRNAs." (PMID 31013606, 2019). "PAR4-/- mice developed less visceral adiposity and glucose intolerance under HFD, featuring smaller adipocytes, fewer macrophages and lower expression of adipogenic (leptin, PPARγ) and pro-inflammatory genes (CCL2, IL-1β) in WAT." (PMID 38652276, 2024). "Our results showed a lower expression of CCL-2 and F4/80, a macrophage infiltration marker, in the RT mice in the early period of FMT, i.e., the pre-stage onset of glucose intolerance." (PMID 36915683, 2023).
metastatic disease (25 papers, 2013 to 2025). "In the metastatic tumors, our study predominantly found a significant increase in macrophages expressing CCL2, MGP, SPP1, and MMP9, which have been previously associated with tumor cell invasion, metastasis, and immunoresistance." (PMID 40858590, 2025). "In metastatic tumors, our study identified a significant presence of macrophages expressing CCL2, MGP, SPP1, and MMP9, which are associated with various aspects of tumor metastasis and may play a crucial role in preparing the metastatic niche for malignant cell growth." (PMID 40858590, 2025). "CCL2 is a chemokine that attracts monocytes to the tumor microenvironment and facilitates the transformation of monocytes to tumor-associated macrophages (TAMs), which contribute to tumor cell growth, angiogenesis, and progression of metastatic disease in various cancers." (PMID 37964011, 2023). "After identifying CCL2 as the most common chemokine expressed in both primary and metastatic disease, we validated CCL2 levels in serum samples from these patients." (PMID 41424784, 2025). "In CAFs from metastatic tumors, a decrease in CCL2, MMP-2, TNC, OPN, and TGFβ levels and an increase in only TIMP1, PDPN, and SPP1 mRNA levels (without an effect on protein levels) was observed after calcitriol treatment." (PMID 38360633, 2024). "C–C motif chemokine ligand 2 (CCL2) is a monocyte chemoattractant that promotes metastatic disease and portends a poor prognosis in many cancers." (PMID 37964011, 2023). "This is also supported by an increased gene and protein expression of the CCL2 in recurrent/metastatic tumors, compared to the primary tumors." (PMID 37964011, 2023). "The results of an Oncomine search indicated that CCL2 was overexpressed in both the tumor and tumor stroma of invasive human BCs and correlated with the development of metastatic disease and poor prognosis." (PMID 37208442, 2023). "This study called for caution when considering CCL2 inhibitors as a single therapy in metastatic diseases and highlighted the tumor microenvironment as a critical determinant of successful antimetastasis therapy." (PMID 37208442, 2023). "This suggests that anti-CCL2 antibody and etoposide significantly suppresses recurrent metastatic disease during the early treatment period." (PMID 37964011, 2023). "Moreover, although the continuous blockade of macrophages constrains tumor progression, cessation of the CCL2 blocking therapy stimulates them to a rapid rebound, leading to accelerated metastatic disease via a mechanism dependent on VEGF-A and IL-6 production monocyte-derived by macrophages." (PMID 31447834, 2019). "Increased cytokines and chemokines, such as TGF-β1, CCL2, and VEGF, have been shown to predict metastatic disease." (PMID 31334111, 2019). "We found a marked production of CCL2 and CXCL1 in the lung, in parallel with macrophage influx, increased metastatic disease and high versican expression in the lung tissue." (PMID 31334111, 2019). "Experimental evidence from various pre-clinical cancer models have been encouraging and indicate that CCL2 and CCR2 are attractive targets for intervention of metastatic diseases." (PMID 26885690, 2016). "Thus, there is a signaling relay from CCL2/CCR2 to CCL3/CCR1 during the process of BC lung metastasis, and blocking the distal part of this signaling relay may have more impact on metastatic disease than blocking upstream targets because of likely lower toxicity." (PMID 37208442, 2023).